FOXP3 (forkhead box P3)
Diseases named in the same sentence as FOXP3 in open-access papers (continued):
Sharing a sentence is not in itself a finding about the gene and the disease.
melanoma (continued). "Here, we show that the modulation of CD4+FOXP3+CD25+regulatory T (Treg) cells upon anti-CTLA4 treatment protects against lymphedema development in patients with melanoma and in a mouse lymphedema model." (PMID 39737964, 2024). "Overall, CD4+ and CD8+ T cells were seen in small but sparsely distributed clusters closer to the skin epidermis of the primary melanoma tumors, and Foxp3+ T cells showed a more homogeneous distribution within the tumor core irrespective of genotype." (PMID 38327091, 2024). "Various tumor types, including pancreatic, breast, ovarian, prostate, lung, and melanoma, have reported the FOXP3 expression, referred to as cancer-FOXP3 (c-FOXP3)." (PMID 38047300, 2024). "We implanted B16F10 melanoma in FOXP3-GFP-DTR mice and gave DT (10 μg/kg) doses as indicated and described earlier." (PMID 39247196, 2024). "Immunohistochemical analysis of melanoma samples revealed that VISTA expression within the tumor area was strongly correlated with FOXP3 expression, an indicator of the presence of Treg cells." (PMID 39482534, 2024). "A study examining the expression of IDO1, PD-L1, and FOXP3-positive regulatory T cells in the melanoma tumor cells showed that these upregulations were driven by CD8+ T cells." (PMID 38632994, 2024). "The present analysis was performed to assess the influence of Treg FoxP3 expression on the prognosis of primary melanoma and to evaluate the correlations with various clinicopathological prognostic factors." (PMID 38928083, 2024). "Somasundaram and colleagues identified that co-localization of FOXP3+ Tregs and MCs in melanoma was correlated with resistance to anti-PD1 therapy and the efficacy of anti-PD1 therapy was improved by depleting MC using the MC inhibitors sunitinib and imatinib." (PMID 39087378, 2024). "They showed that aptamer-sasRNA-mediated transcriptional gene silencing of Foxp3 promotes an antitumor response in combination treatment using a melanoma-bearing mouse model." (PMID 37653036, 2023). "The study was carried out on C57Bl/6 FoxP3-EGFP mice with B16F0 melanoma implanted near the inguinal lymph node." (PMID 38435479, 2023). "The prevention of binding between LAG-3 with MHCII with a cyclic peptide, C25, increases IFN-γ secretion and CD8 T cell infiltration and decreases the FOXP3+ Tregs in both in vivo colon–rectal and melanoma models." (PMID 36829496, 2023). "In murine melanoma, it was demonstrated that FoxP3 shifted the environment toward an immunosuppressive response by modifying the immune system." (PMID 37569676, 2023). "As previous study reported that STAT3 binding site of first intron of the Foxp3 gene was involved in Foxp3 expression in tumor Tregs, such as renal cell cancer, lung cancer, melanoma, colon cancer, and rectal cancer." (PMID 36226375, 2023). "Recently, our group has reported in a murine melanoma model that the antitumor efficacy of these vaccines can be partially recovered (approximately 50%) when the FOXP3 gene was silenced with antisense oligonucleotides before the vaccine administration." (PMID 35628649, 2022). "Another silencing miRNA molecule that influences Treg expression of FOXP3 is miR-126; in a melanoma mouse model, silencing of miR-126 in Tregs activated the anti-tumour response of CD8+ T cells." (PMID 36613640, 2022). "Luckily, old melanoma patients have been found to have a better response to the immune checkpoint inhibitor anti-PD1 due to accumulation of a FOXP3+ Treg cell population." (PMID 36135194, 2022). "A higher percentage of OX40+ cells within FOXP3+CD4+ Tregs was observed in invasive melanoma compared with in situ melanoma, suggesting an enrichment of OX40+ Tregs in invasive melanoma." (PMID 36107619, 2022). "In contrast, in their study, Spranger and co-workers found a strong positive correlation between CD8+ CTLs and FoxP3+ Tregs in melanoma metastases." (PMID 36551965, 2022).
melanoma (continued). "In murine breast and melanoma tumor models, genetic ablation of FOXP3 reduced CCR4+ Treg infiltration and tumor size while also restoring anti-tumor immunity." (PMID 35222362, 2022). "Consistent with these cells likely supporting an immunosuppressive environment, ex vivo co-cultures of melanoma patient-derived B cells with autologous Tcon cells depleted of Tregs resulted in TGF-β-mediated induction of FOXP3+ Tregs." (PMID 35909944, 2022). "CD25-Foxp3+CD4 Tregs significantly increased in melanoma TILs and decreased in dLNs after treatment with anti-PD-1 but not anti-CD80 mAbs, implying PD-1 blockade prevented CD25−Foxp3+CD4 egress from tumor to dLNs." (PMID 35449134, 2022). "Increased infiltration of the tumor boundary by CD8+ cells has been associated with effective clinical responses to melanoma and are consistent with favorable increases in CD8+/FoxP3+ ratios previously observed in melanoma biopsy samples." (PMID 36923305, 2022). "Initially, we observed a significantly increased percentage of FOXP3+ Tregs in melanoma patient compared to healthy volunteer peripheral blood, following anti-CD3/CD28 activation." (PMID 35909944, 2022). "Consistent with previous analyses, we found that inhibition of SPHK1 activity significantly diminished the levels of CD4+CD25+FoxP3+ regulatory T cells (Tregs) and Gr-1+CD11b+ myeloid-derived suppressor cells (MDSCs) in melanoma." (PMID 36050478, 2022). "Triptolide inhibited melanoma growth by reducing Foxp3 mRNA levels in the spleen and auxiliary lymph nodes, as well as TGF-β, IL-10, VEGF and Tregs within the TME." (PMID 36700235, 2022). "IDO/TDO activation-mediated kynurenine (Kyn) accumulation in the TME activates AhR, leading to T cells differentiation into FoxP3+ regulatory T cells and thus melanoma immune escape." (PMID 36003368, 2022). "More importantly, it suggested that the expression of FOXP3 in melanoma metastatic cell lines was markedly highly than that in other cell lines and was mainly localized in the nucleus." (PMID 36235242, 2022). "Using flow cytometry analyses, we observed that the CTLA-4 mAb led to a marked reduction in CD4+CD25+FoxP3+ Tregs in melanoma, consistent with early studies." (PMID 36050478, 2022). "Although statistical significance was achieved for Treg induction by both healthy volunteer and melanoma patient B cells, the overall polarization of FOXP3+ Tregs following the co-cultures was most prominent within the melanoma patient cohort." (PMID 35909944, 2022). "In particular, IDO expression in the melanoma cells seem to play an important role in melanoma progression, and our results also suggest that FoxP3+ Tregs and IDO+ immune stromal cells enhance tumorigenesis in CM." (PMID 34051744, 2021). "Although few in number, other reports have described similar observations of increased frequencies of FoxP3+ cells detected within either tumor or draining lymph node for canine melanoma patients assessed by flow cytometry or by IHC Treg." (PMID 34926643, 2021). "The effector Tregs are highly activated and proliferative with high CTLA-4 expression (FOXP3++CD25++CD45RA−CTLA4+++) in melanoma." (PMID 34806028, 2021). "Previous reports have described increased frequencies of circulating and intratumoral Tregs defined either as FoxP3+CD4+ or CD25+FoxP3+CD4+ T cell subsets for canine melanomas by either flow cytometry analysis or immunohistochemistry (IHC)." (PMID 34926643, 2021). "We also studied the association between IDO and FoxP3+ Tregs, which has not been previously addressed substantially in CM, and we found a positive correlation between IDO+ melanoma cells and FoxP3+ Tregs." (PMID 34051744, 2021). "On the other hand, studies assessing T regs under PD-1/PD-L1 blockade show a distinct downregulation of FoxP3 for melanoma while in gliomas exhausted T regs with high expression of PD-1 failing to suppress effector T cell proliferation accumulated." (PMID 33842304, 2021).
melanoma (continued). "Sequencing of tumor-draining lymph node and tumor Treg cells that present high glucose avidity from B16F10 melanoma-bearing mice revealed reduced expression of Treg cell signature genes, while retaining Foxp3 expression." (PMID 34539668, 2021). "After treatment with LEM extract, the percentage of Treg (CD4+ Foxp3+) cells in the spleen, the mRNA level of Treg cell marker Foxp3 in melanoma tissues, and the level of plasma TGF-β were all significantly reduced." (PMID 33669877, 2021). "By analyzing PBMC from melanoma patients, flow data classifies FOXP3+ cells into FOXP3hi Tregs, FOXP3low naive Tregs, and FOXP3low non-Tregs." (PMID 34806028, 2021). "They contribute to the induction of immune tolerance to melanoma cells and are characterized by a stable expression of the transcription factor FOXP3." (PMID 34066146, 2021). "While the total number of CD4+ T cells (CD45+ CD3+ CD4+) was not significantly different, that of CD4+ regulatory T cells (CD45+ CD3+ CD4+ FoxP3+) was significantly decreased in in AR-silenced YUMM1.7 melanomas." (PMID 33112375, 2021). "Immunohistochemical quantitative analysis of TILs, including expression of CD4, CD8, FOXP3, PD-1, and PD-L1, on melanoma cells was performed." (PMID 33916279, 2021). "The amount of FoxP3+ Tregs was significantly higher in thin and deep melanomas and lymph node metastases of CM, compared with benign nevi (p-values < 0.0001)." (PMID 34051744, 2021). "Decreased CD8+ cells, increased T regulatory cells (Tregs), and subsequent decreased CD8:FoxP3 ratio are more commonly found in the local tumor microenvironment of younger melanoma patients than older patients." (PMID 33373316, 2020). "Accordingly, a similar correlation between Tregs (CD4+FoxP3+) and CD11b+ cells was detected in IDOhigh melanoma cell suspensions as compared to IDOlow samples." (PMID 32782249, 2020). "Although some studies identified a suppressive effect of FOXP3 on melanoma cell lines (through growth inhibition and apoptosis activation), our data are indicating that FOXP3 expression in tumor cells is correlated with a more aggressive biological behavior." (PMID 33274240, 2020). "Multiple studies indicate that the high number of regulatory T cells positive for FOXP3 in melanoma is correlated with a poor outcome; these lymph cells are inhibiting the immune response of other T cells." (PMID 33274240, 2020). "All cases had a significant number of intratumoral FOXP3 lymph cells, this being a mechanism through which melanoma is escaping the immune defense of the host." (PMID 33274240, 2020). "FOXP3 expression in tumor cells seems an independent factor of poor prognosis in melanoma, while regression areas are characterized by a high number of dendritic cells and a low number of regulatory T cells." (PMID 33274240, 2020). "FOXP3, a transcription factor, is mainly expressed in regulatory T cells and, also, in different tumors: melanoma, pancreatic carcinoma, and non-small-cell lung carcinoma." (PMID 33274240, 2020). "Melanoma patients also harbored an enhanced fraction of CD4+Foxp3+ regulatory T cells, while their effector T cells expressed lower levels of the activation marker HLA-DR." (PMID 33344043, 2020). "Our results revealed that Foxp3+ TIL density in melanoma was similar for low- and high-density HEVs." (PMID 32823631, 2020). "We thus resorted to multiplex immunofluorescence (mIF) staining to assess the presence and abundance of GARP+FOXP3+ cells in a serie of 19 melanoma samples." (PMID 32917858, 2020). "As observed in the melanoma tumor model, Tα1 increased the expression of CD8-associated markers (GzmB and Perforin) while reducing the recruitment of Foxp3+CD25+ Treg cells in the lung in combination with anti-PD1 antibody." (PMID 32817121, 2020). "Demethylation of the FOXP3 gene in human melanoma cells precludes the use of this epigenetic mark for quantification of Tregs in unseparated melanoma samples." (PMID 33268350, 2020).
melanoma (continued). "The MMP23 expression of primary melanoma also demonstrated a trend toward an increased proportion of immunosuppressive Foxp3+ regulatory T cells." (PMID 32850314, 2020). "Expression of HLA-G and the presence of FoxP3+ tumor-infiltrating lymphocytes is also believed to contribute to the suppression of effective T cell immune responses in melanoma." (PMID 31134056, 2019). "We have recently shown an association between high HLA-G expression and a high frequency of FoxP3+ tumor-infiltrating lymphocytes in malignant melanoma patients." (PMID 31134056, 2019). "We compared the CTLA-4 protein expression in Tregs (CD4+ Foxp3+) from these patients to five ipilimumab-treated melanoma patients, since they also have disruption of the CTLA-4 pathway and can experience a wide array of autoimmune complications." (PMID 31156616, 2019). "We therefore purified Treg and Tmem cells from B16.F10 melanomas or PBS controls 11 days after subcutaneous implantation into Foxp3-IRES-eGFP reporter mice to produce a plate-based scRNA-seq dataset (see Experimental Procedures)." (PMID 30737144, 2019). "C57BL/6J mice were inoculated i.v. with B16F10 melanoma cells, and Foxp3 expression in the lungs was evaluated by real-time quantitative PCR." (PMID 29899823, 2018). "The complex suppressed the growth of mouse melanoma in vivo, while both platelets and the complex suppressed the accumulation of FoxP3+ regulatory T cells in the tumour." (PMID 27117228, 2016). "Regarding the melanoma samples, Foxp3 expression was confirmed as a predictive marker for survival in patients treated with TILs." (PMID 24741578, 2014). "We found that 12% of stage III and IV metastatic melanomas expressed FOXP3 based on IHC staining of a tissue microarray." (PMID 24406338, 2014). "On the other hand, low level FOXP3 expression (likely below the limit of detection by IHC) is observable by flow cytometry and PCR in most freshly isolated melanoma specimens and in most melanoma cell lines." (PMID 24406338, 2014). "We previously demonstrated FOXP3 expression in human melanoma tissue and cell lines, although the frequency of its expression was not assessed in a large cohort of cases." (PMID 24406338, 2014). "In this analysis, a distinct population of melanoma cells (identified as MCSP+ CD3-CD4- CD31- CD90-) expressing high levels of FOXP3 was identified in some samples, with the frequency of these FOXP3bright cells ranging from 0 – 0.24%." (PMID 24406338, 2014). "This analysis demonstrated that 18/146 (12%) of advanced-stage melanomas contained FOXP3 positive tumor cells." (PMID 24406338, 2014). "Conversely, increased FOXP3 expression has been reported in pancreatic adenocarcinoma, melanoma, hepatocellular carcinoma, leukemia, bladder cancer, thyroid carcinoma and cervical cancer, with no expression in corresponding normal tissue." (PMID 24406338, 2014). "This analysis confirmed the findings obtained with the rabbit polyclonal antibody, with <1% of melanoma cells staining positive for FOXP3." (PMID 24406338, 2014). "These anti-tumor effects of FOXP3 in melanoma cells are consistent with that previously reported in gliomas, breast, prostate, and ovarian cancer cells." (PMID 24406338, 2014). "This has been demonstrated in pancreatic carcinoma and melanoma cell lines, where FOXP3 expression inhibits T cell proliferation in co-culture systems." (PMID 24406338, 2014). "We also found that the frequency of CD4+FoxP3+ Tregs expressing ILT2 was higher in patients with melanoma compared to healthy donors (n = 11 and 11, respectively; P = 0.003)." (PMID 24829758, 2014). "Stable over-expression of FOXP3 in the SK-MEL-28 melanoma cell line reduced cell proliferation and clonogenicity in vitro, and reduced xenograft growth in vivo." (PMID 24406338, 2014).
melanoma (continued). "As previous studies in glioma, breast, prostate and ovarian cancers demonstrated that FOXP3 over-expression induces apoptosis, we examined the effect of FOXP3 over-expression on apoptosis in SK-MEL-28 melanoma cells." (PMID 24406338, 2014). "Reliable down-regulation of FOXP3 in melanoma cell lines proved difficult to accurately evaluate due to its low basal level of expression (data not shown)." (PMID 24406338, 2014). "In our previous study, we reported FOXP3 expression in both metastatic melanoma tissue samples and cell lines derived from tumor samples." (PMID 24406338, 2014). "We next examined FOXP3 mRNA expression in a panel of 25 melanoma cell lines and in normal cultured melanocytes by quantitative PCR (QPCR)." (PMID 24406338, 2014). "We also conducted a flow cytometric analysis of systemic CD4+CD25+FOXP3+ T regulatory cells (Tregs) and histological analysis of melanoma tumors." (PMID 25428727, 2014). "Collectively, these findings demonstrate that FOXP3 over-expression slows the growth of melanoma cells." (PMID 24406338, 2014). "As observed in many aggressive solid tumors, Foxp3+CD4+Treg infiltrated into BrafV600E/Pten-driven melanoma and melanoma-associated tdLN and intratumoral Treg exhibited potent activity of suppressing T cell activation." (PMID 25941586, 2014). "We previously reported FOXP3 expression in human melanomas by demonstration of co-staining of FOXP3 with the melanoma cell surface antigen Melan-A." (PMID 24406338, 2014). "To directly determine the impact of FOXP3 on the growth of melanoma cells, we sought to manipulate FOXP3 levels in melanoma cell lines by RNAi knockdown and vector-mediated over-expression." (PMID 24406338, 2014). "The objectives of this study were to evaluate the frequency of FOXP3 expression in metastatic melanoma, and to determine its role in regulating the growth and survival of melanoma cells." (PMID 24406338, 2014). "The results of the present study, together with our previous report reveal that FOXP3 is expressed at a high level in only a small fraction of melanomas, and in only a minor fraction of cells (<1%) within this subset of tumors." (PMID 24406338, 2014). "Given the low basal expression of FOXP3 in melanoma cell lines, our only means of assessing FOXP3 function in these cells was to over-express the gene." (PMID 24406338, 2014). "Conversely, FOXP3 has been reported to be over-expressed in tumor cells in pancreatic adenocarcinoma, melanoma, leukemia, hepatocellular carcinoma, bladder cancer, thyroid carcinoma and cervical cancer." (PMID 24406338, 2014). "Low levels of FOXP3 mRNA (2-5 copies per 10,000 copies of beta-actin) were detected in 16 of the 25 melanoma cell lines, representing expression 300- to 1000- fold lower than the level observed in Treg cells (2000 copies per 10,000 copies of beta-actin)." (PMID 24406338, 2014). "Using reporter mice that bear melanoma, authors were able to differentiate between “ex” and “current” Foxp3+ Treg cells." (PMID 23874336, 2013). "Generally, sentinel nodes with metastases were demonstrated to contain more FOXP3+ cells than tumor-free ones in melanoma, breast or gastric cancer." (PMID 23418928, 2013). "The expression of Foxp3 in tumor cells has also been recently reported in pancreatic cancer, melanoma and other tumor cell lines." (PMID 24179494, 2013). "On the basis of these observations we decided to make an amendment of our study protocol on dendritic cell-based vaccination in advanced melanoma by adding low-dose TMZ in an attempt to deplete the Foxp3+Treg population." (PMID 23725550, 2013). "In the same line of thought, a melanoma specific hypomethylation has been described for the first intron of FOXP3 gene, demethylated in regulatory T cell clones and in melanoma cells, compared to other cancer cells such as lung and colorectal carcinoma cells." (PMID 24086527, 2013).